SDC1 (syndecan 1)
Diseases named in the same sentence as SDC1 in open-access papers (continued):
Sharing a sentence is not in itself a finding about the gene and the disease.
tumor (continued). "Known inducers of angiogenesis, such as vascular endothelial growth factor and syndecan-1, were among the genes that were higher expressed in the tumor epithelium of African-American patients than European-American patients." (PMID 19225562, 2009). "In a wide range of carcinomas it has been shown that a low expression of syndecan-1 on tumor cell surfaces correlates with increasing metastatic potential and poor prognosis." (PMID 19527490, 2009). "Given that heparanase promotes an aggressive tumor phenotype and that it can also regulate the location of syndecan-1, we examined the effect of heparanase expression on syndecan-1 localization within the nucleus." (PMID 19305494, 2009). "Decreasing SDC-1 expression was correlated with advanced tumour stage and an increased metastatic tendency of the cancer cells in a wide range of tumours." (PMID 19865524, 2009). "It was recently discovered that heparanase can also enhance shedding of the syndecan-1 heparan sulfate proteoglycan from the surface of tumor cells." (PMID 19305494, 2009). "In contrast, increased SDC-1 expression and correlation with a higher degree of malignancy, as well as expression in connective tissue surrounding the tumour, has also been reported in other tumours." (PMID 19865524, 2009). "A novel significant correlation between decreased syndecan-1 staining on tumor cells and increased stromal fascin staining was detected." (PMID 18590537, 2008). "Out of 131 patients, in 65 cases syndecan-1 was expressed on less than 25% of the tumor cells, and in 49 cases between 25% to 75% of tumor cells were stained." (PMID 18590537, 2008). "Only 8.75% of the patients retained syndecan-1 expression within their tumour cells while having reactive stroma-expressing syndecan-1 (E+S+)." (PMID 18542065, 2008). "We also examined the 5 year survival rate and median survival times for each of the tumor syndecan-1 scoring categories." (PMID 18590537, 2008). "On the tumor cells, syndecan-1 was localized around the entire cell membrane and in many cells appeared to be cytoplasmically located." (PMID 18590537, 2008). "A fraction of patients have abnormal up-regulation of syndecan-1 on stromal cells in the vicinity of the tumor, and this also correlates with poor prognosis." (PMID 18590537, 2008). "Based on a four-tiered scale, moderate to strong positive staining of tumour cells was observed for Sdc1 in 108 out of 150 (72%), for c-met in 69 out of 142 (48.6%) and for E-cad in 101 out of 149 (67.8%) evaluable DCIS samples." (PMID 17244359, 2007). "Expression of syndecan-1, E-cadherin and c-met was detected immunohistochemically using a tissue microarray in tumour specimens from 200 DCIS patients." (PMID 17244359, 2007). "Tissue microarray analysis revealed strong positive staining of tumour cells for syndecan-1 in 72%, E-cadherin in 67.8% and c-met in 48.6% of DCIS." (PMID 17244359, 2007). "Notably, a notable correlation was identified between SDC1 levels and key components within the tumor microenvironment, including CD4+/CD8 + T lymphocytes, cancer-associated fibroblasts (CAFs), and myeloid-derived suppressor cells (MDSCs)." (PMID 42098527, 2026). "Additionally, Fibroblast–tumor cell co-culture systems and functional assays were employed to investigate the paracrine role of SDC1." (PMID 40616092, 2025). "In tumor stemness analysis, we found that SDC1 was positively correlated with the scores for DNA, EREG-methss, DMPss, ENHss, RNAss and EREG in STES, THTM, but SDC1 expression was negatively correlated with the scores for DNA, EREG-methss, DMPss, ENHss, RNAss and EREG in TGCT, LUAD in TCGA dataset." (PMID 41364407, 2025). "Moreover, we explored the mechanism behind the significant role of SDC1 expressed in tumor cells during tumor progression." (PMID 41364407, 2025).
tumor (continued). "In addition, syndecan-1, a transmembrane heparan sulfate proteoglycan, has been specified as a potential marker for tumor progression, with reduced expression correlating with increased invasiveness as reported for a case series for CSCC." (PMID 41394861, 2025). "Certain proteoglycans, such as syndecan-1 and glypican-1, promote tumor growth and dissemination by enhancing growth factor signaling and cell migration, whereas others, including decorin and lumican, inhibit tumor progression by modulating immune responses and collagen fibrillogenesis." (PMID 41303704, 2025). "In view of this, the present study successfully constructed an in situ self-reactive gold nanocluster SDC1 shRNA-targeted nucleic acid delivery system in tumor cells by taking advantage of the reductive microenvironment at the tumor site, which significantly inhibited TNBC angiogenesis." (PMID 41209699, 2025). "SDC1 has been shown to play a tumor-suppressor role in CRCs." (PMID 39869563, 2025). "MDK seems to be involved in tumor cell communication through binding several of its receptors, including syndecan 1 (SDC1), SDC4, NCL, and LRP1, and MDK from tumors seems to bind to NCL on macrophages and lymphocytes, though the functional consequences have not been explored." (PMID 40429950, 2025). "Specifically, the reducing microenvironment at the tumor site was exploited to reduce the GNCs precursor to a GNCs, which can form a complex with SDC1 shRNA at the tumor site to achieve targeted delivery of SDC1 shRNA at the tumor site." (PMID 41209699, 2025). "Interestingly, when comparing interaction numbers within 200 μm to those within 100 μm radius, we found substantial increases in the interactions between SDC1+ plasma B cells and tumor cells, and between classical plasma B cells and tumor cells." (PMID 40470730, 2025). "The presence of SDC1 or CD138 in tumor cells could provide prognostic insights when combined with clinical parameters." (PMID 41364407, 2025). "In fact, selection of CD38+/CD138+ cells from MM patients enriches for a highly malignant population, while cell surface-shedding of the proteoglycan and accumulation of Syndecan-1/CD138 fragments in the bone-marrow tumour milieu and in circulation sets up a detrimental chemoresistance loop." (PMID 39980017, 2025). "Notably, syndecan‐1 (SDC1) and glypican‐1 (GPC1) are well‐established modulators of the tumor microenvironment and are frequently associated with exosomal cargo in aggressive cancers." (PMID 41039818, 2025). "We further propose that SDC1 may regulate cellular functions within the tumor by modulating the differentiation of fibroblasts and macrophages." (PMID 41209699, 2025). "Consequently, if it is feasible to utilize nucleic acid delivery to achieve a reduction in the expression level of SDC1 in tumor cells." (PMID 41209699, 2025). "The survival curve of SDC1 expression in tumor cells is particularly noteworthy." (PMID 40616092, 2025). "Chen indicated that T cells in PDAC have enriched expression of CCL5 which could induce tumor cell migration through interaction with SDC1." (PMID 41364407, 2025). "This suggests a possible decrease in syndecan-1 expression as tumor aggressiveness increases." (PMID 39728992, 2024). "Furthermore, the mechanism was verified that SDC1-LB-MSN-HNK induced tumor cell apoptosis through the mitochondrial apoptosis pathway." (PMID 38338418, 2024). "In our study, a statistically significant relationship between histological grade and the presence of syndecan-1 in the stroma was found, suggesting that tumors with greater malignancy express this marker in the stroma, as described in other human tumor studies." (PMID 39728992, 2024). "The research aimed to explore two specific markers, syndecan-1 and E-cadherin, which can help scientists understand how aggressive the tumor might become." (PMID 39728992, 2024).
tumor (continued). "For example, attenuation of Erk phosphorylation and FSP1/S100A4 expression were evidently more effective by the 140 and 543 mutants, whereas syndecan-1, tumor fibrosis (i.e., collagen deposition), and deposition of collagen IV, were increased by the 140/543 mutants vs WT Hpa2." (PMID 39695102, 2024). "Thus, both syndecan-1 and E-cadherin are potentially valuable tools in clinical practice, contributing to the prediction of tumor behavior and the choice of interventions that improve clinical outcomes." (PMID 39728992, 2024). "Compared with mice treated with the free drug and LB-MSN-GEM/HNK treatment, tumor growth was significantly inhibited with SDC1-LB-MSN-GEM/HNK treatment, which was induced by superior depletion of dense stroma and the synergistic GEM and HNK to effectively kill cancer cells." (PMID 38338418, 2024). "However, several antibody-drug conjugates (ACDs) have been developed to deliver cytotoxic agents to tumor cells with elevated surface levels of syndecan-1." (PMID 37046595, 2023). "They replicated the upregulation of the syndecan-1 transcript in tumor samples." (PMID 37370735, 2023). "Immune escape may be the reason why TNBC patients with positive expression of SDC1 in tumor cells had a poor prognosis." (PMID 37069585, 2023). "Moreover, high expression of syndecan-1 in CAFs correlated with tumor progression in specific cancer types from breast, colon, prostate, ovary and lung." (PMID 36906534, 2023). "Overall, these data together showed that COL1A1, COL1A2, and COL6A3 are the key molecules that might regulate the tumor pEMT phonotype by interacting with SDC1 and accelerate the malignant progression of cancer patients." (PMID 38002057, 2023). "TILs were regulated differently by SDC1 in tumor cells and CAFs." (PMID 37069585, 2023). "Syndecan-1 expression was present both in the primary tumor and metastases." (PMID 37370735, 2023). "Moreover, the extent and pattern of expression of syndecan-1 were compared between primary tumors and paired metastases and correlated with the tumor intrinsic subtype." (PMID 36088392, 2023). "Remarkably, we found that the chemokine CCL5 secreted by PD1 + T cells could combine with SDC1/4 on the surface of all PD-L1 + tumor clusters (Tumor1-6)." (PMID 36944944, 2023). "In this study, we identified that hypoxia-like tumor cells may also act on SDC1/CD138+ IgG1 PCs by secreting ANGPTL4." (PMID 37138324, 2023). "However, when they cultured T47D cells in contact with SDC1-transfected fibroblasts, the tumor growth was significantly increased." (PMID 36980680, 2023). "Notably, Sdc-1 not only determines tumor cell-autonomous functions, but also affects the tumor microenvironment, including the immune cell phenotype, extracellular matrix (ECM) organization by stromal fibroblasts, and tumor angiogenesis." (PMID 36980251, 2023). "Even more, Kaplan-Meier survival curves of progression-free survival (PFS) demonstrated inferior survival probabilities in patients with high tumor expression of PXDNL (p=0.0001) and SDC1 (p<0.0001) and low tumor expression of FBLN1 (p=0.0087), FBLN5 (p=0.026) and ADAMTS8 (p<0.0001)." (PMID 37056938, 2023). "Interestingly, MK-expressing tumor cells can interact with B cells and their subpopulation, plasma cells, through SDC1 and ITGA4-ITGB1, respectively." (PMID 37835544, 2023). "We speculate that hypoxic tumor cells may secrete ANGPTL4 to communicate with SDC1+ PCs, affecting their differentiation, survival, and/or antibody secretion." (PMID 37138324, 2023). "In particular, genes encoding collagen, including COL1A1, COL1A2, COL6A1, and COL6A3, are upregulated in tumor tissue and also highly expressed in late-stage cancer patients; they are predicted to interact with SDC1 and SDC4 in tumor cells to promote the pEMT phenotype of tumors." (PMID 38002057, 2023). "On the other hand, the enhanced expression of SDC1 on 4T1 tumor cells increased brain metastasis." (PMID 36980680, 2023).
tumor (continued). "It has been shown that SDC1 promotes the transformation of tumor ECs into an angiogenic phenotype." (PMID 36358833, 2022). "Furthermore, we also concluded that down-regulated of S100A6 (F = 3.52, P=0.0164), S100A10 (F = 5.36, P=0.0015), S100A16 (F = 6.69, P=0.00027), and SDC1 (F = 4.02, P=0.00849) were effectively related to lower tumor stage." (PMID 35342420, 2022). "As our previous reports show, the expression of SDC1 increased with the increase of tumor grade." (PMID 35669186, 2022). "Its presence in tumor cells increases with tumor aggressiveness, and it can influence the function of receptor tyrosine kinases, intracellular phosphokinases, and DNA synthesis and alleviates the protective potential of syndecan-1 against HCC." (PMID 35186754, 2022). "Finally, the role of Sdc-1 in the progression to a malignant phenotype apparently depends not only on its expression in the tumor cells, but also in the stroma, providing a rationale for studies in a co-culture setting." (PMID 35155241, 2022). "We hypothesized that CXCL6, S100A2, and SDC1 lead to tumor progression and immune escape by raising gamma delta T cells and reducing CD8+T cells, but this hypothesis needs further verification." (PMID 35432485, 2022). "For this reason, the determination of the tumor marker CEA together with markers of organ dysfunction such as SDC1 or GPC4 may appear advantageous in estimating the prognosis of CRC since they can provide complementary information." (PMID 36353562, 2022). "Studies also indicated that the increased expression level of SDC1 could promote the growth, invasion and metastasis of tumor cells." (PMID 35392402, 2022). "Of these syndecans, syndecan-1 is the most investigated prognostic marker in several tumor types." (PMID 35128576, 2022). "SDC1 is positively correlated with tumor subtype and grade according to our study and could thus become a prognostic biomarker." (PMID 35037689, 2022). "Importantly, several preclinical and clinical studies have demonstrated that therapies targeting Sdc-1 can inhibit the aggressive behavior of tumor cells." (PMID 35155241, 2022). "It has been observed that Sdc-1 shedding potentially affects tumor growth and metastasis." (PMID 35155241, 2022). "Stromal syndecan-1 expression in most tumor types is a poor prognostic factor." (PMID 35378690, 2022). "As reported, the disorder of SDC1 expression could effectively influence tumor cells invasion and metastasis." (PMID 35342420, 2022). "In virtually all tumor types, stromal syndecan-1 is an indicator of poor prognosis." (PMID 33921767, 2021). "Syndecan-1 is a cell-surface protein with significant roles in various aspects of tumor function." (PMID 31540870, 2021). "Importantly, as both SDC-1 and heparanase participate in exosome generation, heparanase inhibition reduces tumor growth as well as exosome-derived tumor recurrence." (PMID 35118073, 2021). "Consistent with our results, others have reported that SDC1 regulates EMT in tumor cells." (PMID 34208075, 2021). "CD138, also known as syndecan-1, is a peptide that inhibits tumour growth." (PMID 33917771, 2021). "It promotes tumor progression and metastasis by enhancing the synthesis and shedding of syndecan-1." (PMID 33669066, 2021). "As such, it is hypothesized that radiotherapy or chemotherapy may indeed increase extracellular SDC-1 deposition, subsequently leading to tumor recurrence and metastasis." (PMID 35118073, 2021). "The aim of the present study was therefore to test the hypothesis that nuclear SDC1 is involved in regulating epithelial-mesenchymal plasticity in tumor cells." (PMID 34208075, 2021). "Altogether, our results suggest that in tumor cells, Sdc-1 KD decreases the expression of angiogenic factors, in a mechanism that could involve several pro-angiogenic molecules such as VEGF, PDGF, IL-8, and miR10b." (PMID 34070901, 2021).
tumor (continued). "Likewise, correlations between tumor characteristics, SDC-1 localization and prognostic significance in the setting of different cancers warrant further research." (PMID 35118073, 2021). "However, the role of tumor cell-autonomous Sdc-1 expression in the regulation of angiogenesis in the context of tumor-endothelial interactions has not yet been elucidated." (PMID 34066023, 2021). "Based on recent data showing that SDC1 can translocate to the cell nucleus in tumor cells, we set out to study whether nuclear SDC1 might play a role in regulating epithelial-mesenchymal plasticity." (PMID 34208075, 2021). "However, it is also clear from the known distribution of syndecan-1 that besides being enriched in some tumors and tumor microenvironments, it is widespread in normal epithelia." (PMID 33921767, 2021). "As the membrane-anchored SDC-1 undergoes both nuclear translocation as well as extracellular shedding, emerging studies have focused on location-specific roles played by this protein in tumor pathology." (PMID 35118073, 2021). "Along with a collagenolytic phenotype (decreased type I collagen synthesis and increased MMP activity), these senescent human breast stromal fibroblasts display overexpression of the proteoglycan syndecan-1 that represents a poor prognostic factor for tumor development when expressed in the stroma." (PMID 33924197, 2021). "Frequently, but certainly not uniformly, loss of syndecan-1 correlates with tumor aggression, grade, invasive behavior and poorer prognosis." (PMID 33921767, 2021). "Immunoprecipitation studies suggest that the majority, if not all, of the IGF-1R in tumor cells is associated with Sdc1, potentially making SSTNIGF1R a highly specific cancer therapy." (PMID 34778093, 2021). "Kras* pancreas tumor cells showed highly active macropinocytosis, which could be down-regulated by inactivation of Kras* or SDC1." (PMID 34249755, 2021). "As a second approach to study this, we analyzed whether nuclear translocation of SDC1 would affect EMT characteristics in mesenchymal tumor cells." (PMID 34208075, 2021). "Recently, it was discovered that SDC1 translocates into the cell nucleus in certain tumor cells." (PMID 34208075, 2021). "Additionally, a side-by-side comparison was made for sequential sections of a tumor-bearing mouse liver immunostained for syndecan-1 and irradiated for multi-elemental analyses." (PMID 34349175, 2021). "Combined clinical application of MMP inhibitors for the purpose of impeding SDC-1 shedding along with chemotherapy may offer a unique approach aimed at preventing formation of microenvironments conducive to tumor recurrence." (PMID 35118073, 2021). "Moreover, it has been found that the amount of nuclear SDC1 is reduced after expression of the enzyme heparanase, which is upregulated in many cancers and promotes tumor progression and metastasis." (PMID 34208075, 2021). "This stromal syndecan-1 could be produced by mesenchymal cells or could be shed from epithelial cells into the tumor stroma." (PMID 33669066, 2021). "Furthermore, SDC1 depletion with shRNAs dramatically impaired colony-forming ability, and significantly inhibited tumor growth of subcutaneous xenografts." (PMID 34249755, 2021). "Moreover, endoglin expression in tumor cells was positively correlated with E-cadherin, β-catenin, and Syndecan-1." (PMID 33276489, 2020). "Syndecan-1 had an exceptionally high AUC (Area Under the Curve on the receiver operating characteristic) value of 0.81 and a sensitivity and specificity of 71% and 91%, respectively, for distinguishing these high- and low-grade tumours." (PMID 33121160, 2020). "Also, in combination with dexamethasone it was able to inhibit myeloma tumor growth in vivo through dual targeting of the tumor and its microenvironment via the heparanase/syndecan-1 axis." (PMID 31963505, 2020).